ZNF784 (zinc finger protein 784)
Description:
May be involved in transcriptional regulation.
Synonyms: MGC75238
Tractability: PROTAC: UniProt records ubiquitination sites on it.
Gene: Protein-coding gene on chromosome 19 (55,620,741 to 55,624,566, reverse strand). Ensembl gene ENSG00000179922.
Subcellular location: Nucleus
Subcellular location (Human Protein Atlas): Nucleoplasm
Gene Ontology:
Molecular function: protein binding; sequence-specific double-stranded DNA binding; DNA-binding transcription activator activity, RNA polymerase II-specific; RNA polymerase II cis-regulatory region sequence-specific DNA binding
Biological process: regulation of transcription by RNA polymerase II; positive regulation of transcription by RNA polymerase II
Cellular component: nucleus
Genetic constraint (gnomAD): Loss-of-function variants: 5 observed, 3.35 expected, observed/expected ratio (o/e) 1.49, 90% interval 0.7 to 1.93. That is too few expected variants to judge how well the gene tolerates losing a copy. Missense variants: 501 observed, 397.82 expected, observed/expected ratio (o/e) 1.26, 90% interval 1.17 to 1.36. Synonymous variants: 231 observed, 179.25 expected, observed/expected ratio (o/e) 1.29, 90% interval 1.16 to 1.44.
Homologues: Orthologues: chimpanzee ZNF784 (99% identical), macaque ZNF784 (97% identical), pig ZNF784 (87% identical), dog ZNF784 (86% identical), guinea pig ZNF784 (79% identical), rat Zfp865 (78% identical), mouse Zfp784 (77% identical). Paralogues in human: ZNF646 (34% identical), ZNF319 (19% identical), ZNF34 (19% identical), ZNF774 (19% identical), ZNF287 (18% identical), ZNF572 (18% identical), WIZ (18% identical), ZNF407 (18% identical), ZNF530 (18% identical), ZNF17 (18% identical), ZNF697 (18% identical), ZNF768 (18% identical), and 38 more.
Diseases named in the same sentence as ZNF784 in open-access papers:
ZNF784 is named in the same sentence as 2 diseases in open-access papers, as found by Europe PMC text mining. Sharing a sentence is not in itself a finding about the gene and the disease.
ZNF784 shares sentences with these, for which no sentence is quoted: cancer (1 paper); leukemia (1).